TLR4 (toll like receptor 4)
Diseases named in the same sentence as TLR4 in open-access papers (continued):
Sharing a sentence is not in itself a finding about the gene and the disease.
mastitis (continued). "The results showed that, unlike in the mastitis group, no significant redness and swelling were observed in the mammary glands of TLR4−/− and GSDMD−/− mice." (PMID 40552401, 2025). "Moreover, proteins like complement C4 (C4), BRCA1, TLR4, MBLA, and calcium voltage-gated channel auxiliary subunit alpha2delta 1 (CACNA2D1) have been found during mastitis in buffalo and are also reported as potential biomarkers in livestock mastitis." (PMID 39858163, 2025). "Indeed, in bovine mastitis, HMGB1 and HSP70 levels in milk are elevated and the TLR4 signaling pathway is activated." (PMID 39609525, 2024). "In this study, artemisinin inhibited the activation of TLR4/NF-κB pathways in E. coli–infected MAC-T cells, and this may be a potential mechanism for artemisinin treatment of mastitis." (PMID 35893774, 2022). "Furthermore, the PCC value of immunofluorescence colocalization of TLR4 and SYK in bovine mastitis tissue was 0.8857 (0.6 < PCC < 1.0), which was highly correlated." (PMID 36672605, 2022). "Moreover, SYK protein level was also significantly down-regulated in bovine mastitis tissue, and protein levels of NLRP3, TLR4 and IL-1β were significantly up-regulated." (PMID 36672605, 2022). "In addition, coimmunoprecipitation results confirmed the presence of the TLR4–SYK signaling pathway in bovine mammary gland tissues and bMCEs to participate in the immune cascade response to mastitis and the same phenomenon in bMECs with LPS or GBS." (PMID 36672605, 2022). "However, the increase in the expression of TLR4 in milk phagocytes isolated from SCM and CM mastitis was also significant, which indicates that this receptor is also critical for the elimination of the invading pathogens." (PMID 34235202, 2021). "In addition, based on published literature, we concluded that TLR4, IL-1β, IL-6, TNF-α and MYD88 are key players in NF-κB signaling and also have an essential role in mastitis development." (PMID 32927884, 2020). "We found that SIRT7 can attenuate LPS-induced upregulation of TLR4 and TAB1 and can also inhibit TAK1 phosphorylation, indicating that SIRT7 is involved in the TLR4-TAK1-TAB1-mediated NF-κB signaling pathway during cattle mastitis occurrence." (PMID 31285783, 2019). "On the other hand, we also explored the possibility that we should compensate for the lack of TLR4 signaling during S. aureus mastitis by preconditioning with LPS." (PMID 28791009, 2017). "Statistical analysis of transcript and protein level expression changes indicated that 10 genes, namely TLR4, MyD88, IL-6, and IL-10, were up-regulated, while, CD14, TNF-α, MD-2, IL-β, NF-κB, and IL-12 were significantly down-regulated in mastitis tissue in comparison with normal tissue." (PMID 25706977, 2015). "In the present study, we compared the gene expression of several key molecules involved in TLR4 activation and the NF-κB signaling pathway in mammary tissue from Chinese Holstein cattle with and without mastitis." (PMID 25706977, 2015). "Toll-like receptor (TLR)-4 is known to be responsible for the recognition of LPS, and thus mediates proinflammatory cytokine production by activating inflammatory signatures, such as NF-κB and NLRP3, which have been shown to participate in the pathogenesis of mastitis." (PMID 37069691, 2023). "In addition, TLR4, IL-1β, IL-6, TNF-α, MYD88 and NF-κB might be a useful addition as markers in mastitis control strategies." (PMID 32927884, 2020). "However, following resolution of mastitis, milk production capacity was reduced in wild-type mice compared to those deficient in TLR4, raising the possibility that mastitis-associated lactation insufficiency may be due in part to TLR4-mediated inflammation, rather than bacterial infection per se." (PMID 29705830, 2018). "Similarly, as TLR4 activation by LPS is protective against E. coli mastitis, this study aimed to boost TLR2-induced immune response of the murine mammary microenvironment by LTA to protect the host against S. aureus mastitis." (PMID 28791009, 2017).
mastitis (continued). "In the current investigation, qRT-PCR was used to measure the levels of antioxidant (CAT, GPX1, Keap1, OXSR1, ATOX1, GST, and Nrf2) and immune (IFN-γ, IL-4, TNF-α, MYD88, CCL5, TLR4, TLR9, LTF, and PRLR) genes in Barki ewes that were resistant and non-resistant to mastitis." (PMID 40542007, 2025).
epilepsy (90 papers, 2011 to 2026). A brain disorder characterized by episodes of abnormally increased neuronal discharge resulting in transient episodes of sensory or motor neurological dysfunction, or psychic dysfunction. "Pre-clinical investigations have revealed that elevated levels of TLR4 correlate with a heightened risk and severity of epilepsy, along with a greater probability of developing resistance to anticonvulsant treatments." (PMID 40809181, 2025). "The current review highlights the roles of the IL-1/IL-1R1/IL-1Ra pathway and HMGB1/TLR4 pathway as crucial mechanisms underlying epileptogenesis and sustaining epilepsy, making them potential therapeutic targets." (PMID 41155637, 2025). "As a result, our further screening demonstrated that pro-inflammatory cytokines (PICs), such as IL-1β, IL-6, and TNF-α, and the TLR4/NF-κB pathway were associated with APS' effects in treating epilepsy." (PMID 38405667, 2024). "A clinical study suggested that increased HMGB1 or TLR4 expression is associated with a higher risk and severity of epilepsy, as well as an increased likelihood of anticonvulsant drug resistance." (PMID 39046369, 2024). "TLR2, 3, and 4 have been described in cortical neurons and, for TLR4, a seizure-promoting role in epilepsies associated with inflammation has been shown." (PMID 35507634, 2022). "Further analysis revealed considerably increased Toll-like receptor 4 (TLR4), associated with reduced γ-aminobutyric acid type A receptor α1 (GABAARα1) and microglia enhanced in the epilepsy–migraine comorbidity rat." (PMID 36358363, 2022). "A clinical study suggested that increased HMGB1 or TLR4 expression correlated with a higher risk and severity of epilepsy, as well as the increased possibility of anti-seizure medication resistance." (PMID 35837232, 2022). "Is epilepsy–migraine comorbidity related to TLR4 microglial activation associated with CSD and inflammation?" (PMID 36358363, 2022). "This study aimed to investigate the association of serum high-mobility group box-1 (HMGB1) and toll-like receptor 4 (TLR4) expressions with the risk of epilepsy as well as their correlations with disease severity and resistance to anti-epilepsy drugs." (PMID 31241711, 2019). "In conclusion, both HMGB1 and TLR4 expressions were correlated with increased risk and severity of epilepsy and their level was higher in patients resistant to anti-epilepsy drugs." (PMID 31241711, 2019). "In conclusion, both increased HMGB1 and TLR4 expressions correlated with higher risk and severity of epilepsy as well as the elevated possibility of anti-epilepsy drug resistance." (PMID 31241711, 2019). "Both serum HMGB1 (P<0.001) and TLR4 (P<0.001) expressions were higher in epilepsy patients than in HCs, and they displayed good predictive values for risk of epilepsy." (PMID 31241711, 2019). "Furthermore, the mRNA levels of Irf3, Tlr4, Myd88, and Irak4 genes—encoding innate immune system markers essential for maintaining neuronal excitation/inhibition balance and implicated in epilepsy—were examined." (PMID 40608247, 2025). "Furthermore, epilepsy has been linked to Toll-Like Receptor 4 (TLR4), a pattern recognition receptor involved in innate immunity, by way of its involvement in neuroinflammation." (PMID 40540445, 2025). "Based on the present results, ferroptosis-related hub genes NFE2L2, PTGS2, IL6, JUN, HMOX1, and TLR4 have good diagnostic value for epilepsy and may be potential early biological diagnostic targets." (PMID 37946105, 2023). "Summary of studies on the HMGB1/TLR4 and IL-1β/ IL-1R pathways and their association with epilepsy." (PMID 35837232, 2022). "Interestingly, higher circulating levels and increased expression of HMGB1 and TLR4 in epileptogenic tissue have been associated with increased risk and severity of epilepsy." (PMID 34198762, 2021). "Moreover, in comparison with wild-type mice TLR4-deficient mice develop less severe epilepsy following status epilepticus." (PMID 31959173, 2020).
epilepsy (continued). "Therefore, we conducted this case-control study to investigate the association of serum HMGB1 and TLR4 expressions with the risk of epilepsy as well as their correlations with disease severity and anti-epilepsy drugs resistance." (PMID 31241711, 2019). "Activation of the innate immune system, such as the application of the TLR4 agonist LPS, is known to be potently epileptogenic in mouse models, and chronic inflammation has been implicated in mesial temporal lobe epilepsy with hippocampal sclerosis, a frequently occurring, acquired type of epilepsy." (PMID 36672163, 2023). "TLR4 is mainly expressed in microglia and mediates microglial activation, suggesting the role of microglia in linking immunity and epilepsy." (PMID 39851521, 2025). "The toll-like receptor 4 (TLR4) pathway serves as a critical mediator between neuroinflammatory processes and epilepsy development." (PMID 41327653, 2025). "Regarding the role of TLR4 and NF-κB in epilepsy, previous studies have demonstrated that the overexpression of HMGB1, which signals through TLR4 and activates NF-κB, exacerbates epileptogenesis." (PMID 40718441, 2025). "Further research is needed to explore the long-term effects of TLR4 inhibition in epilepsy treatment." (PMID 40718441, 2025). "The expression of TLR2 and TLR4 was significantly greater in the epilepsy group compared to the low-grade glioma group." (PMID 40809181, 2025). "In this review, we mainly focus on the IL-1β/IL-1R1/IL-1Ra pathway and HMGB1/TLR4 pathway, in which recent advances in knowledge have been made for epilepsy." (PMID 41155637, 2025). "In summary, the HMGB1/TLR4 pathway and IL-1/IL-1R1/IL-1Ra pathway partly share similar mechanisms in neuroinflammation of epilepsy." (PMID 41155637, 2025). "In epilepsy, TLR4 signaling triggers glial activation and cytokine release via the MyD88–NF-κB pathway, enhancing neuronal excitability and BBB permeability." (PMID 41007696, 2025). "Towards clinical translation, we carefully reviewed existing substances and drugs targeting the IL-1β/IL-1R1/IL-1Ra pathway and HMGB1/TLR4 pathway and their effects on epilepsy models and patients." (PMID 41155637, 2025). "Kamaşsk and colleagues found that TLR4 levels were remarkably greater in patients with severe epilepsy, suggesting a relationship between epilepsy severity and TLR4 expression levels." (PMID 40809181, 2025). "In conclusion, chrysophanol demonstrated remarkable neuroprotective and antiepileptic effects at a dose of 10 mg/kg in stress-exacerbated PTZ-induced epilepsy following the TLR4/NFκB -Nrf2/HO-1 and BDNF/VEGF pathways." (PMID 39650161, 2024). "HMGB1 is mainly involved in the epilepsy pathophysiology by interacting with the primary receptor TLR4." (PMID 39046369, 2024). "Studies show that epigallocatechin gallate (EGCG), quercetin, fisetin, and luteolin significantly lower TLR-4/NF-κB and IL-1β levels in hippocampal neurons of a pilocarpine-induced mouse epilepsy model." (PMID 39329119, 2024). "Specifically, flavones primarily counter epilepsy through interactions with pathways such as NF-κB p65, the TLR4/MyD88/NF-κB axis, PPAR-γ, MAPK, HMGB1, IGF1R, NLRP3, and MAO-B, which are essential in mitigating neuroinflammation." (PMID 39329119, 2024). "Many studies have shown that the HMGB/RAGE/TLR4/NF‐κB pathway is involved in both epilepsy and toxoplasmosis." (PMID 39046369, 2024). "Significant upregulation of TLR4 expression has also been observed in epilepsy patients and animal models." (PMID 39598325, 2024). "Gene expression levels of the HMGB1/RAGE/TLR4/NF‐κB signalling pathway, which is effective in both epilepsy and toxoplasmosis, were determined in patients with idiopathic epilepsy." (PMID 39046369, 2024). "When the body’s cells are stimulated by external factors (such as epilepsy), TLR4 is activated, which can then activate IKKs to phosphorylate them." (PMID 39598325, 2024).
epilepsy (continued). "Among these, the HMGB1/RAGE/TLR4/NF‐κB signalling pathway has been shown by clinical and preclinical studies to play a significant role in epilepsy, in addition to its role in many neurological diseases." (PMID 39046369, 2024). "In this research, we identified six characteristic genes associated with ferroptosis in epilepsy: NFE2L2, PTGS2, IL6, JUN, HMOX1, and TLR4." (PMID 37946105, 2023). "We have identified six feature genes (IL6, PTGS2, HMOX1, NFE2L2, TLR4, and JUN) strongly associated with ferroptosis in epilepsy, suggesting their potential as biomarkers for the diagnosis of temporal lobe epilepsy." (PMID 37946105, 2023). "GABA type A receptor α1 binding and negative regulation of TLR4 leads to epilepsy–migraine comorbidity, and TLR4 is a key intermediate in epilepsy–migraine comorbidity." (PMID 37283931, 2023). "A growing body of research demonstrates that HMGB1 is generated from activated astrocytes and microglia, or neuron, subsequently interacts with the primary receptor TLR4 to involve in the pathophysiology of epilepsy." (PMID 38187384, 2023). "Quercetin showed its anti-inflammatory action by suppressing the TLR4/NF-kB signaling pathway in the animal models of experimental epilepsy." (PMID 36672083, 2023). "The neuroimmune inflammatory response mediated by IL-1β/IL-1R1 and HMGB1/TLR4 signaling pathways plays an important role in the pathogenesis of epilepsy." (PMID 37305762, 2023). "Existing research has shown a significant increase in serum levels of TLR4 in cases of drug-resistant epilepsy, indicating its potential as a novel epilepsy biomarker." (PMID 37946105, 2023). "The anti-inflammatory potential of EGCG, observed on lithium-pilocarpine-induced epilepsy, is mediated by inhibiting the TLR4/NF-kB signaling pathway." (PMID 36672083, 2023). "An important question is, why does TLR4 contribute to epilepsy–migraine comorbidity downstream of GABAARα1?" (PMID 36358363, 2022). "Collectively, the data indicated that the neuronal GABAARα1 bound TLR4, and regulated its expression, likely contributing to signal activation in epilepsy–migraine comorbidity." (PMID 36358363, 2022). "A study (2018) showed that the HMGB1/TLR4/NF-κB pathway mediates the activation of microglia in epilepsy." (PMID 35656438, 2022). "Combined data indicated that, in the epilepsy–migraine comorbidity group, GABAARα1 was involved in regulating seizures and migraine attacks, while TLR4 was involved in migraine attacks." (PMID 36358363, 2022). "For preliminary observation of the involvement of TLR4 and GABAARα1 in epilepsy–migraine comorbidity, we determined the TLR4 and GABAARα1 expression patterns in different tissues of the brain." (PMID 36358363, 2022). "The present study provided evidence that the TLR4/TRAF6/NF-κB signaling pathway is positively associated with neuroinflammation and apoptosis in pilocarpine-induced epilepsy." (PMID 35647304, 2022). "It proved that TLR4 was involved in the processes of epilepsy, migraines, and epilepsy–migraine comorbidity, especially the latter two." (PMID 36358363, 2022). "After quantification, we found that in the migraine and epilepsy groups, GABAARα1 in the medullary dorsal horn and the trigeminal ganglion was more highly expressed in the epilepsy group, and TLR4 in the migraine group was higher." (PMID 36358363, 2022). "Here, HMGB1/TLR4 and IL-1β/IL-1R inflammasomes in the pathogenesis of epilepsy are reviewed and future perspectives are outlined." (PMID 35837232, 2022). "The role of microglias in epilepsy is gradually being recognized, and the TLR4 signaling pathway is considered to be one of the important bridges connecting innate immunity and acquired immunity." (PMID 35493845, 2022). "The TLR4/NF-κB signaling pathway is responsible for inflammatory responses in different disorders, including epilepsy." (PMID 35647304, 2022).